SMYD3 (SET and MYND domain containing 3)
Diseases named in the same sentence as SMYD3 in open-access papers (continued):
Sharing a sentence is not in itself a finding about the gene and the disease.
ovarian carcinoma (15 papers, 2019 to 2025). A malignant neoplasm originating from the surface ovarian epithelium. "For example, in ovarian cancer, loss of SMYD3 results in the upregulation of CDKN2A (p16) and CDKN2B (p15) genes." (PMID 35406445, 2022). "SMYD3 inhibition concordantly led to S phase arrest and increased apoptosis of ovarian cancer cells." (PMID 39762343, 2025). "In ovarian cancer, shRNA-mediated knockdown of SMYD3 decreases spheroid invasion and adhesion by suppressing integrin subunit beta 6 (ITGB6) and integrin subunit alpha M (ITGAM)." (PMID 39482529, 2024). "SMYD3 also facilitated implant metastasis of ovarian cancer cells via increasing the expression of ITGB6 and ITGAM." (PMID 37386026, 2023). "We also verified that the transcription levels of the histone methylation-related genes EZH2, KDM8, STED5, and SMYD3 decreased significantly after MLN4924 treatment of ovarian cancer cells." (PMID 35864225, 2022). "In ovarian cancer spheroids, SMYD3 was found bind to H3K4me3 at the ITGB6 and ITGAM promoter regions to upregulate the expression of ITGB6 and ITGAM, which was verified to enhance the invasion and adhesion of ovarian cancer spheroids." (PMID 34621667, 2021). "ChIP assays showed increased SMYD3 and H3K4me3 promoter binding at the ITGB6 and ITGAM gene loci in ovarian cancer spheroids and decreased binding with SMYD3 knockdown." (PMID 33637115, 2021). "According to our previous study, SMYD3 is overexpressed in ovarian cancer ascites spheroids compared with primary ovarian cancer tissues." (PMID 34621667, 2021). "Inhibition of ITGB6 and ITGAM directly also resulted in decreased ovarian cancer spheroid adhesion and invasion, and this was restored with re-expression of SMYD3, ITGB6, and ITGAM." (PMID 33637115, 2021). "Our previous studies showed that SET and MYND domain-containing protein 3 (SMYD3) expression was higher in ovarian cancer spheroids than in monolayers." (PMID 34621667, 2021). "The authors showed that SMYD3 is overexpressed in ovarian cancer spheroids, and that SMYD3 is critical to their invasive capacity." (PMID 33637115, 2021). "The SMYD3-H3K4me3-integrin pathway plays an important role in the pathogenesis of implantation metastasis in ovarian cancer." (PMID 34621667, 2021). "Knock down of SMYD3 in ovarian cancer tissues leads to upregulation of CDKN2B (p15INK4B), CDKN2A (p16INK4), CDC25A and CDKN3 as members of cyclin-dependent kinase inhibitors (CDK)." (PMID 33333978, 2020). "Inducing apoptosis via silencing of SMYD3 has also been observed in ovarian cancer in vivo and has been accredited to the upregulation of CD40LG and downregulation of BIRC3." (PMID 33333978, 2020). "In ESCC, glioma, lung and ovarian cancers patients carrying low SMYD3-expressing tumors, overall survival [OS] is significantly longer than in those with high SMYD3-expressed cancers." (PMID 31935919, 2020). "SMYD3 promotes ovarian cancer proliferation and interferes with apoptosis in vitro and in vivo by regulating cell cycle checkpoints and apoptosis-related proteins though SMYD3-H4K20me3-CDKN2A pathway and SMYD3-H3K4me3-BIRC3 pathway." (PMID 31417652, 2019). "We then performed RTCA and plate colony formation assays to validate the effect of SMYD3 on ovarian cancer cell proliferation using stable SMYD3-knockdown cell lines." (PMID 31417652, 2019). "We firstly built nude mice subcutaneous tumor model by injecting human ovarian cancer cell line subcutaneously to test the function of SMYD3 in vivo." (PMID 31417652, 2019).
ovarian carcinoma (continued). "Our study is the first report that SMYD3 is essential for ovarian cancer proliferation and tumorigenesis, indicating the potential of SMYD3 as a new epigenetic therapeutic target for ovarian cancer." (PMID 31417652, 2019). "The immunohistochemistry results showed that SMYD3 expression was significantly higher in ovarian cancer tissues than in normal ovarian surface epithelium." (PMID 31417652, 2019). "In this study, we aimed to investigate SMYD3 expression in ovarian cancer and its potential role and regulatory mechanism in cell proliferation and apoptosis." (PMID 31417652, 2019). "CCK-8 assay, Real-time cell analysis (RTCA), colony formation assay, cell cycle and apoptosis tested by Flow cytometer were employed to test the effects of SMYD3 on cell proliferation and apoptosis in ovarian cancer cell lines." (PMID 31417652, 2019). "In conclusion, we demonstrated that SMYD3 is overexpressed in ovarian cancer compared with normal ovarian epithelial tissue." (PMID 31417652, 2019). "We analyzed SMYD3 expression in normal ovarian surface epithelium from 10 women and ovarian cancer tissues from 55 women by immunohistochemistry." (PMID 31417652, 2019). "Using real-time PCR, we found that silencing SMYD3 significantly decreased the mRNA levels of CCNA2, CCNB2, CCND2, CDK1 and CDK2 (p<0.05) but increased the mRNA levels of WEE1 (p<0.05), suggesting an essential role for SMYD3 in ovarian carcinoma proliferation." (PMID 31417652, 2019). "After silencing SMYD3, the proliferation of ovarian cancer cells was significantly inhibited in vitro." (PMID 31417652, 2019). "In order to study the effect of SMYD3 on ovarian cancer cell line proliferation, siRNAs were constructed to knockdown SMYD3." (PMID 31417652, 2019). "CDC25A was significantly overexpressed (p=0.02) and BIRC3 was significantly down-regulated (p=0.02) after SMYD3 knockdown in ovarian cancer PDX model." (PMID 31417652, 2019). "SMYD3 knockdown suppressed the adhesion and invasion of ovarian cancer spheroids." (PMID 33637115, 2021). "Conversely, SMYD3 knockdown resulted in decreased ovarian cancer cell proliferation." (PMID 33637115, 2021). "To determine why SMYD3 and ITGB6 could make ovarian cancer spheroids more invasive, we downregulated the expression of SMYD3 and ITGB6 in 3D-cultured HEY and A2780 cells." (PMID 34621667, 2021). "Interestingly, attenuating the expression of SMYD3 and ITGB6 also decreased the release of latent TGFβ1 from ovarian cancer spheroids, which further demonstrated the regulatory roles of SMYD3 and ITGB6 in TGFβ1 pathway activation." (PMID 34621667, 2021). "In addition, the SMYD3-specific small-molecule inhibitor BCI-121 suppressed ovarian cancer cell proliferation." (PMID 31417652, 2019). "SMYD3 was also highly expressed in the other ovarian carcinoma cell lines." (PMID 31417652, 2019). "Then, we investigated SMYD3 expression in ovarian cancer cell lines and HOSEpiC." (PMID 31417652, 2019). "Therefore, we selected another ovarian cell line, A2780, which had the highest SMYD3 expression among all ovarian cell lines tested to further investigate the role of SMYD3 in promoting ovarian cancer proliferation." (PMID 31417652, 2019). "Furthermore, the specific SMYD3 small-molecule inhibitor BCI-121 can effectively inhibit the proliferation of ovarian cancer cells." (PMID 31417652, 2019). "From these studies, SMYD3 may be a rational therapeutic target in the treatment of ovarian cancer." (PMID 33637115, 2021). "In addition, TGFβ1 could also upregulate the expression of SMYD3 and ITGB6 in return to form a positive feedback loop with the SMYD3/ITGB6/TGFβ1 pathway to enhance the metastasis of ovarian cancer spheroids." (PMID 34621667, 2021).
ovarian carcinoma (continued). "Using a 3D culture model to mimic the suspended growth conditions in ascites, we found that SMYD3 could enhance the adhesion and invasion of ovarian cancer spheroids and promote metastasis of ovarian cancer in vivo by upregulating the expression of ITGB6 and ITGAM." (PMID 34621667, 2021). "Therefore, SMYD3 can repress ovarian cancer progression both in nude mice model and PDX model." (PMID 31417652, 2019). "Thus, SMYD3 contributed to a more aggressive phenotype of ovarian cancer." (PMID 31417652, 2019). "Thus, SMYD3 is a promising epigenetic therapeutic target for ovarian cancer." (PMID 31417652, 2019). "Finally, knocking down SMYD3 could inhibit ovarian cancer growth in nude mice subcutaneous tumor model and PDX model." (PMID 31417652, 2019). "However, in lung cancer and pancreatic cancer, SMYD3 is localized in the cytoplasm and activates the ERK pathway by methylating MAP3K2.7, 11-13 Although SMYD3 is tightly connected to carcinogenesis, there are few articles about the role of SMYD3 in ovarian cancer." (PMID 31417652, 2019). "This was indicative of the importance of the positive feedback loop between SMYD3/ITGB6/TGFβ1 in enhancing the invasion and adhesion of ovarian cancer spheroids as well as cell–cell communication in these models." (PMID 38254117, 2024). "Our study also emphasized the significance of choosing SMYD3 and ITGB6 as potential targets for the treatment of ovarian cancer transcoelomic metastasis." (PMID 34621667, 2021). "Compared with 2D-cultured HEY and A2780 cells, the corresponding 3D-cultured cells showed higher expression of SMYD3 and ITGB6, which indicated that the ovarian cancer spheroids had a more invasive phenotype." (PMID 34621667, 2021). "In conclusion, we detailed one essential pathway that contributed to the SMYD3- and ITGB6-mediated enhancement of invasion and adherence in ovarian cancer spheroids." (PMID 34621667, 2021). "However, the exact role of SMYD3 in the progression of ovarian cancer is still unknown." (PMID 31417652, 2019). "In order to investigate the effect of SMYD3 inhibition on human epithelial ovarian cancer repression, we established ovarian cancer PDX model with human ovarian cancer tissue." (PMID 31417652, 2019). "3D spherical models of ovarian cancer have been used to shed light on the impact of both integrin beta-6 (ITGB6) and SET and MYN-domain containing 3 (SMYD3) on the activation of the TGFβ1/Smad3 pathway and downstream upregulation of N-cadherin and downregulation of E-cadherin." (PMID 38254117, 2024). "SMYD3 and ITGB6 activated the TGFβ1/Smad3 pathway and then induced the upregulation of Snail, Vimentin and N-cadherin and the downregulation of E-cadherin in 3D-cultured ovarian cancer spheroids." (PMID 34621667, 2021). "In this report, we found that SMYD3 and ITGB6 could promote the release and activation of latent TGFβ1 and increase the phosphorylation of Smad3 activated by TGFβ1 in ovarian cancer spheroids." (PMID 34621667, 2021). "According to reports and our research base, we speculated that SMYD3/ITGB6 promotes the invasion and adhesion of ovarian cancer spheroids by changing the configuration of TGFβ1-LAP and then activating TGFβ1." (PMID 34621667, 2021). "Thus, the SMYD3/ITGB6/TGFβ1 positive feedback loop drove the upregulation of Snail and N-cadherin, which promoted invasion, adhesion and EMT progression during ovarian cancer metastasis." (PMID 34621667, 2021). "Thus, our study unmasked the mechanism of SMYD3- and ITGB6-induced ovarian cancer metastasis and provides new ideas for targeted ovarian cancer treatment." (PMID 34621667, 2021). "SMYD3 knockdown resulted in decreased mRNA levels of CCNA2, CCNB2, CCND2, CDK1, and CDK2, and increased mRNA levels of WEE1, leading to S phase arrestin SMYD3-depleted ovarian cancer cells." (PMID 33637115, 2021).
ovarian carcinoma (continued). "Using ovarian cancer PDX models, SMYD3 was identified to induce ovarian cancer growth 97, and to promote metastasis and reduce ascites volume in ovarian cancer PDX models 98, suggesting that SMYD3 may be related to the development of ovarian cancer." (PMID 32742495, 2020). "Hence, SMYD3 and ITGB6 could not only activate latent TGFβ1 but also increase the release of latent TGFβ1 from 3D-cultured ovarian cancer spheroids." (PMID 34621667, 2021). "Therefore, SMYD3 and ITGB6 could stimulate the TGFβ1/Smad3 pathway and regulate the expression of N-cadherin, Snail, Vimentin, E-cadherin in ovarian cancer spheroids and promote the EMT process." (PMID 34621667, 2021). "Our results demonstrated that the SMYD3/ITGB6/TGFβ1-Smad3 positive feedback loop could promote the invasion and adhesion of ovarian cancer spheroids by upregulating the expression of N-cadherin, Snail, and Vimentin and downregulating the expression of E-cadherin." (PMID 34621667, 2021). "As downstream targets of the TGFβ1/SMAD3 pathway and essential participants in EMT promotion, N-cadherin, Vimentin, E-cadherin and Snail were found to be regulated by SMYD3 and ITGB6 and could contribute to enhanced invasion and adhesion in ovarian cancer spheroids." (PMID 34621667, 2021). "Moreover, SMYD3 and ITGB6 could facilitate the release of latent TGFβ1 from 3D-cultured ovarian cancer spheroids." (PMID 34621667, 2021). "We chose the ovarian cancer cell lines HEY and A2780 to further investigate the localization of SMYD3 compared with those in HOSEpiC via a cell immunofluorescence assay, which showed that SMYD3 was predominantly localized in the cytoplasm in A2780 cells and HOSEpiC." (PMID 31417652, 2019).
gastric cancer (13 papers, 2017 to 2025). A primary or metastatic malignant neoplasm involving the stomach. "SMYD3 was involved in the regulation of cell proliferation of gastric cancer and was positively associated with poor prognosis in this cancer." (PMID 31548876, 2019). "In gastric cancer cells, Wtn3a stimulation promotes SMYD3 transcript expression, through the direct recruitment of β-catenin/TCF4 complex in Wnt3a-treated SGC7901 gastric cancer cells." (PMID 31935919, 2020). "Moreover, SMYD3 expression is significantly elevated in gastric cancer tissues and is correlated with aggressive clinical features and poor prognosis." (PMID 39482529, 2024). "Conversely, in MGC-803 gastric cancer cells, SMYD3 down-regulation induces G2/M-phase arrest." (PMID 31935919, 2020). "In addition, SMYD3 expression was positively associated, respectively, with the metalloproteinases MMP-2 and MMP-9 expression in pancreatic and gastric cancer tissues." (PMID 31935919, 2020). "Since it is not clear that how SMYD3-elicited transcriptionally repressive program functions in cancer, we used gastric cancer (GC) as a model to investigate the roles of SMYD3-H4K20me3." (PMID 37386026, 2023). "While a deep characterization of SMYD3 functions in different cancer stem cells is still lacking, initial findings in gastric carcinoma stem cells show that SMYD3 controls Wnt induced activation of the ASCL2 gene, a master regulator of stem cell maintenance." (PMID 31935919, 2020). "Importantly, MMP9 is one of the downstream target genes of SMYD3 (SET and MYND domain containing protein 3), the histone H3-K4 di-/tri- and H4-K5-methyltransferase, and overexpression of SMYD3 can induce MMP9 expression in human tumor models, e.g., gastric cancer." (PMID 34943943, 2021).
liver cancer (12 papers, 2015 to 2024). An epithelial or non-epithelial malignant neoplasm that arises from the liver. "Inhibition of SMYD3 can prevent muscle loss and fiber size reduction and has been shown to promote the proliferation and metastasis of liver cancer." (PMID 36555340, 2022). "Downregulation of the RIZ1 H3K9 methylase by SMYD3 has been linked liver cancer cell expansion in vitro, through DNA methylation of its promoter." (PMID 36520265, 2022). "Our results indicate that the SMYD3/NuRD complex is involved in liver cancer proliferation and metastasis." (PMID 36575438, 2022). "In summary, our study demonstrates that SMYD3 specifically associates with the NuRD (MTA1/2) complex to form a complex in liver cancer cells, providing new insights into how SMYD3 regulates transcription by coordinating with distinct partner protein complexes." (PMID 36575438, 2022). "Related, a recent report indicated that SMYD3 also methylates K5 on H4 tails in breast and liver cancer cell lines, suggesting a possible role of H4K5me3 in SMYD3-driven oncogenic processes." (PMID 26350217, 2015). "Moreover, SMYD3 is considered a biomarker for the poor prognosis of liver cancer, and these traits make SMYD3 an ideal target for drug discovery initiatives." (PMID 39286779, 2024). "To date, SMYD3 overexpression in cancerous tissues has been reported to occur in liver cancer, colon cancer, breast cancer, pancreatic cancer, prostate cancer, bladder cancer, gastric cancer, malignant glioma, esophageal squamous cell carcinoma, chronic lymph cell leukemia, and cervical cancer." (PMID 39286779, 2024). "In addition, we demonstrated that SMYD3 promotes cell proliferation, invasion, and tumorigenesis in vivo and in vitro and found that its expression is markedly upregulated in human liver cancer." (PMID 36575438, 2022). "Our data provide a molecular basis for understanding the pathophysiological function of SMYD3, and its inhibition could have widespread application for liver cancer treatment." (PMID 36575438, 2022). "Interestingly, research has shown that SMYD3 not only plays an important role in tumors, such as liver cancer, but also acts as a key regulator of the cardiovascular system." (PMID 31968646, 2020). "In addition, previous studies found that SMYD3 not only plays an important role in tumors, such as liver cancer, but also participates in metabolism, the action of steroid hormones and the cardiovascular system, in which it is a key regulator." (PMID 31968646, 2020). "SMYD3 was originally identified as a methylase of H3K4 and it is involved in the proliferation of colon and liver cancer cells." (PMID 36520265, 2022). "SET and MYND domain-containing protein 3 (SMYD3) has been shown to promote the progression of various types of human cancers, including liver cancer; however, the detailed molecular mechanism is still largely unknown." (PMID 34301921, 2021). "The results revealed that expression of SMYD3 was upregulated, while IGFBP4 was downregulated in liver cancer tissues compared to noncancerous liver tissues." (PMID 36575438, 2022).